RPS16P4 (ribosomal protein S16 pseudogene 4)
Synonyms: RPS16_2_363
Gene: Transcribed processed pseudogene on chromosome 3 (37,196,204 to 37,196,666, forward strand). Ensembl gene ENSG00000231449.
Diseases named in the same sentence as RPS16P4 in open-access papers:
RPS16P4 is named in the same sentence as 1 disease in open-access papers, as found by Europe PMC text mining. Sharing a sentence is not in itself a finding about the gene and the disease. The quoted sentences say what the papers report.
schizophrenia (1 paper, 2024). A major psychotic disorder characterized by abnormalities in the perception or expression of reality. "From total 66 DEGs, we identified 11 (16%) as pseudogenes, which comprised two main groups: mitochondrial pseudogenes increased in females (MTND1P23, MTCO1P12, MTCO1P40, and MTND2P28) and ribosomal pseudogenes increased in male schizophrenia patients (RPS4XP22, RPS16P4, and RPS28P7)." (PMID 39068467, 2024).